EGFL6 (EGF like domain multiple 6)
Diseases named in the same sentence as EGFL6 in open-access papers (continued):
Sharing a sentence is not in itself a finding about the gene and the disease.
breast carcinoma (8 papers, 2012 to 2025). "Further, their results indicated that EGFL6 can also induce epithelial-mesenchymal transformation (EMT) of breast cancer and maintain the expression of breast cancer-related stem cells." (PMID 32624687, 2020). "The expression of EGFL6 in breast cancer is related to tumor node metastasis (TNM) stages of breast cancer." (PMID 32624687, 2020). "Studies also show that the higher the malignant degree of breast cancer, the higher the expression of EGFL6." (PMID 32624687, 2020). "EGFL6 promotes the invasive phenotype of breast cancer by inducing the epithelial–mesenchymal transition (EMT)." (PMID 32008086, 2020). "Various studies show that EGFL6 plays an important role in the occurrence and development of breast cancer." (PMID 32624687, 2020). "SPECT/CT imaging revealed that EGFL6 was targeted to the tumor-epithelial interface of human breast carcinoma xenografts, and the binding was specific to the EGFL6 peptide sequence." (PMID 26045973, 2014). "Following four rounds of in vivo selection in human MDA-MB-435 breast cancer xenografted mice, peptide 3-G03 was discovered with significant homology to a putative secreted protein termed EGFL6." (PMID 26045973, 2014). "Because a peptide with homology to EGFL6 was identified by the in vivo selection, it was assumed that the xenografted breast cancer cell line expressed EGFL6." (PMID 26045973, 2014). "Although EGFL6 protein expression was demonstrated by immunoblot, the affinity and specificity of the corresponding EGFL6 peptide for human breast carcinomas needed to be assessed." (PMID 26045973, 2014). "Identification of a peptide that bound to human breast carcinoma cells expressing EGFL6 offered the potential that the EGFL6 peptide could be used in vivo to detect tumorigenesis in xenografts expressing the potential tumor vasculature ligand." (PMID 26045973, 2014). "Their results suggest EGFL6 may play a role in angiogenesis of breast cancer." (PMID 32624687, 2020). "Two genes upregulated in tumors from all races and with a role in tumorigenesis were PPP1R14C, which was shown to promote breast cancer cell proliferation, maintaining GSK3 in an inactive state in triple-negative breast cancer, and EGFL6, which regulates angiogenesis and tumor growth." (PMID 37686244, 2023). "We also identified two genes, epidermal growth factor-like domain-containing protein 6 (EGFL6) and follicular dendritic cell secreted protein (FDCSP), which were highly down-regulated after treatment with metformin compared to placebo in postmenopausal breast cancer survivors." (PMID 40374694, 2025).
colorectal cancer (6 papers, 2012 to 2024). A primary or metastatic malignant neoplasm that affects the colon or rectum. "Consistent with a protumorigenic role for EGFL6, increased EGFL6 expression is also associated with poor prognosis in ovarian, breast, and colorectal cancers." (PMID 39312740, 2024). "EGFL6 has now been shown to promote the growth of numerous tumor types, including breast, head and neck, and colorectal cancer." (PMID 39312740, 2024). "In vitro and in vivo experiments have shown that EGFL6 affects the proliferation of colorectal cancer cells, regulates cell cycle, and inhibits apoptosis." (PMID 32624687, 2020). "Zhang and colleagues 44 first linked the function of EGFL6 to the Wnt/β-catenin pathway in studying the potential mechanism of EGFL6 in colorectal cancer." (PMID 32624687, 2020). "Recently, some studies have showed EGFL6 could modulate cancer cell proliferation, and metastasis in colorectal cancer and different cancer types." (PMID 33726836, 2021). "EGFL6 plays an important role in the occurrence and development of colorectal cancer." (PMID 32624687, 2020).
meningioma (5 papers, 2012 to 2022). A generally slow growing tumor attached to the dura mater. "The sensitivity of serum EGFL6 levels in patients with meningioma relative to healthy controls was 81%, and the specificity was 100% at a cutoff value of 64.38 pg/ml." (PMID 23285163, 2012). "Through analysis of the microarray results, several signaling pathways associated with tumorigenesis of meningioma were generated and EGFL6 was found overexpressed in benign meningioma tissues and serum." (PMID 23285163, 2012). "EGFL6 was identified as one of the most up-regulated genes in fibroblastic meningioma by microarray analysis." (PMID 23285163, 2012). "Another important result of our study is to find EGFL6 overexpression in benign meningioma tissues and serum." (PMID 23285163, 2012). "We presented evidence that patients with benign meningioma had high levels of tissue EGFL6 mRNA and serum EGFL6 concentration." (PMID 23285163, 2012). "Significantly, EGFL6 expression in fibroblastic meningiomas increased 68- and 73-fold by microarray and qRT-PCR respectively when compared with arachnoidal tissue." (PMID 23285163, 2012). "ROC analysis indicated high sensitivity (81%) and high specificity (100%) of serum EGFL6 for patients with meningioma." (PMID 23285163, 2012). "Among different WHO grades of meningiomas, it was significant that serum EGFL6 was detected with higher levels in patients with benign meningiomas than those with atypical and anaplastic tumors." (PMID 23285163, 2012). "We performed ROC analysis to evaluate the sensitivity and specificity of serum EGFL6 levels for meningioma." (PMID 23285163, 2012). "In order to show the distribution of serum EGFL6 in patients with meningioma more clearly, a scatter plot graph was generated." (PMID 23285163, 2012). "Our study enriched the EGFL6 gene expression profile by determining EGFL6 mRNA levels in meningioma with different WHO grades and subtypes and extending the survey of EGFL6 mRNA levels in tumor tissues." (PMID 23285163, 2012). "We found that several growth factors including EGFL6, IGF1, FGF2, FGF7, FGF9, and FGF11 were overexpressed in fibroblastic meningioma, especially EGFL6 gene with extremely high expression in benign meningioma tissues." (PMID 23285163, 2012). "qRT-PCR analysis indicated that besides fibroblastic meningioma, other subtype benign meningioma also had high levels of EGFL6 mRNA." (PMID 23285163, 2012). "Considering overexpression of EGFL6 and activation of PI3K/Akt pathway in fibroblastic meningioma, we speculated that EGFL6 played a role in the pathogenesis of benign meningioma via activating PI3K/Akt pathway." (PMID 23285163, 2012). "We are very careful in describing EGFL6 as a biomarker for meningioma." (PMID 23285163, 2012). "Firstly, we investigated serum EGFL6 levels in patients with meningiomas." (PMID 23285163, 2012). "When compared with brain arachnoidal tissue, 82- (P<0.001), 75- (P<0.001), 83- (P<0.001), 84- (P<0.001), and 77-fold (P<0.001) increases of EGFL6 mRNA levels were observed in meningotheliomatous, angiomatous, psammomatous, transitional, and secretory meningiomas, respectively." (PMID 23285163, 2012). "EGFL6, also known as MAEG, is highly expressed in fetal tissues and meningioma." (PMID 23285163, 2012). "We next investigated whether EGFL6 mRNA levels were up-regulated in meningiomas with other histological subtypes." (PMID 23285163, 2012). "EGFL6 was one of the most up-regulated genes in fibroblastic meningioma by microarray analysis." (PMID 23285163, 2012). "However, EGFL6 mRNA was detected with low levels in atypical meningiomas (1.9-fold, vs brain arachnoidal tissue)." (PMID 23285163, 2012). "We also presented evidence that EGFL6, a secreted protein, belonging to the epidermal growth factor (EGF) repeat superfamily, was overexpressed in benign meningioma tissues and serum." (PMID 23285163, 2012).
meningioma (continued). "It was found that serum EGFL6 concentrations in patients with benign meningiomas were not significantly correlated with tumor sizes quantified by magnetic resonance imaging (MRI) (r = −0.1964, P = 0.2896)." (PMID 23285163, 2012). "Although high levels of EGFL6 in benign meningioma, due to small sizes of atypical and anaplastic tumors in our study, it is not easy to use EGFL6 to help discriminate benignancy or malignancy of meningioma before surgery or at early time points." (PMID 23285163, 2012). "Previous evidence demonstrated that EGFL6 transcript was detected in two meningiomas, and not observed in a glioma and a malignant lymphoma." (PMID 23285163, 2012).
nasopharyngeal carcinoma (4 papers, 2018 to 2020). A carcinoma arising from the nasopharyngeal epithelium. "For instance, EGFL6 was recently reported to accelerate the growth and metastasis of nasopharyngeal carcinoma by regulating the expression of the Akt pathway." (PMID 32008086, 2020). "As for the level of EGFL6 in serum, two studies have reported EGFL6 level was highly expressed in nasopharyngeal carcinoma (120 pg/ml vs. 46 pg/ml or so) and oral squamous cell carcinoma (304.48 ± 194.55 pg/mL vs. 178.69 ± 102.96 pg/mL; p < 0.001)." (PMID 32008086, 2020). "To date, EGFL6 has been reported to be upregulated in many tumors such as breast, lung, and nasopharyngeal cancer and participates in the tumor progression and metastasis." (PMID 32008086, 2020). "We first detected the expression of EGFL6 in non‐cancerous nasopharyngeal tissues (N) and nasopharyngeal carcinoma (NPC)." (PMID 30444069, 2018). "As a potential ligand of EGFR, EGFL6 could downregulate the expression of E-cadherin, upregulate the expression of F-actin and Vimentin, and promote metastasis of nasopharyngeal carcinoma through the EMT signal pathway." (PMID 32983976, 2020). "Nevertheless, how EGFL6 participates in the progression and tumorigenesis of nasopharyngeal carcinoma (NPC) remains unclear." (PMID 30444069, 2018).
lung adenocarcinoma (3 papers, 2020 to 2024). A carcinoma that arises from the lung and is characterized by the presence of malignant glandular epithelial cells. "For instance, EGF-like domain multiple 6 secreted by lung adenocarcinoma cells can enhance the EMT process, activate the Wnt/β-catenin and PI3K/AKT/mTOR pathways, promoting lung adenocarcinoma cell proliferation, migration, and invasion capabilities." (PMID 38571500, 2024). "Heightened expression of epidermal growth factor-like domain multiple 6 (EGFL6), a secretory protein, in lung adenocarcinoma cells amplifies their proliferative, migratory, and invasive capacities." (PMID 39512767, 2024). "In patients with lung adenocarcinoma undergoing surgical treatment, the levels of EGFL6 in tumor tissues are correlated with the presence of BM and TNM staging." (PMID 39512767, 2024). "Furthermore, EGFL6 secretion from human lung adenocarcinoma cells enhances the differentiation of osteoclasts from bone marrow mononuclear macrophages (BMMs) in murine models." (PMID 39512767, 2024).
ovarian tumor (3 papers, 2020 to 2024). "EGFL6 is expressed in tumor endothelial cells as well as in cancer epithelial cells of the breast, colon, and ovarian tumors." (PMID 39312740, 2024). "Analyses of effects showed that EGFL6 lead to a decrease in the KOV3ip1 ovarian tumor load and significant decreases in tumor tissue proliferation index and tumor microvascular density." (PMID 32624687, 2020). "Egfl6 expression by ovarian tumor cells reduces the efficacy of a-PD-L1 immune therapy." (PMID 39312740, 2024). "EGFL6 can promote the occurrence and development of ovarian tumors." (PMID 32624687, 2020).
colon cancer (2 papers, 2021 to 2022). "For example, EGFL6 and COMP are highly associated with colon cancer." (PMID 35178071, 2021).
hepatocellular carcinoma (2 papers, 2012 to 2020). A malignant tumor that arises from hepatocytes. "The angiogenic function of EGFL6 was first implicated in hepatocellular carcinoma." (PMID 32008086, 2020).
melanoma (2 papers, 2020 to 2024). A malignant, usually aggressive tumor composed of atypical, neoplastic melanocytes. "FMNL2 activity has recently been associated with exosome release downstream of an EGFL6 signaling pathway, and previous proteomic screens found FMNL2 in exosomes released by melanoma cells." (PMID 38891874, 2024).
oral squamous cell carcinoma (2 papers, 2020). "Chuang and colleagues 45 investigated the relationship between plasma EGFL6 level and clinicopathological features of patients with oral squamous cell carcinoma." (PMID 32624687, 2020). "Their results suggest that EGFL6 plays an important role in the development of oral squamous cell carcinoma." (PMID 32624687, 2020). "In addition, EGFL6 is overexpressed in oral squamous cell carcinoma 45, nasopharyngeal carcinoma 46, lung cancer 47, benign meningioma 41 and other tissues." (PMID 32624687, 2020). "The detection of EGFL6 protein can be used as a tumor marker to predict risk for oral squamous cell carcinoma in patients without this disease." (PMID 32624687, 2020).
adenoma (1 paper, 2018). A neoplasm arising from the epithelium. "The knockdown of Egfl6 or expression of Lrig3 abolished the sensitivity of adenoma cells to EGFR inhibition." (PMID 29872037, 2018). "RT-PCR analyses confirmed that Egfl6, Flna, and Troy were upregulated, and that Lrig3 was downregulated in CHIR99021-treated organoids and adenoma-derived organoids." (PMID 29872037, 2018).
anaplastic meningioma (1 paper, 2012). A WHO grade III meningioma characterized by the presence of malignant morphologic features, including malignant cytology and a very high mitotic index (20 or more mitoses per ten high power fields). "We observed that EGFL6 mRNA levels were significantly increased in benign meningioma when compared with either brain arachnoidal tissue or atypical or anaplastic meningiomas." (PMID 23285163, 2012). "Quantitative real-time PCR demonstrated that benign meningiomas had significantly higher levels of EGFL6 mRNA than brain arachnoidal tissue and atypical and anaplastic meningiomas (P<0.001)." (PMID 23285163, 2012).
benign meningioma (1 paper, 2012). A grade I, slowly growing meningioma. "The mean serum EGFL6 concentration in the female patients with benign meningioma was slightly higher than that in male patients, but the difference was not significant." (PMID 23285163, 2012). "We also presented evidence that EGFL6 was overexpressed in benign meningioma tissues and serum." (PMID 23285163, 2012). "The role of EGFL6 in the pathogenesis of benign meningioma remained unknown." (PMID 23285163, 2012).
colorectal polyps (1 paper, 2021). "As colorectal polyps usually progress to colorectal tumors, EGFL6 could be as a suitable biomarker for early CRC detection." (PMID 33726836, 2021). "Notably, in the AOM-induced mice model, EGFL6 started to express when colorectal polyps occurred, and the expression of EGFL6 increased as colorectal polyps progressed." (PMID 33726836, 2021).
deafness (1 paper, 2018). An inherited or acquired condition characterized by the complete loss of the ability to hear from one or both ears. "Multiple ECM genes are also upregulated in the upper-bulge compartment, including Aspn, Crispld1, Egfl6, and the deafness-related ECM genes Col4a3 and Col4a4." (PMID 30355452, 2018).
endometrial cancer (1 paper, 2025). Primary or metastatic malignant neoplasm involving the endometrium (mucous membrane that lines the endometrial cavity). "These experiments utilized endometrial cancer cells and tissues, with EGFL6 knockdown resulting in reduced tumor growth." (PMID 40868176, 2025).
hemangioma (1 paper, 2017). A benign vascular lesion characterized by the formation of capillary-sized or cavernous vascular channels. "EGFL6 is expressed primarily in the vasculature and is not expressed by SKOV3 cells, so to assess the effect of EGFL6 in-vivo, we initiated tumors using SKOV3 cells co-injected with control hemangioma stem cell (HemSC) derived endothelial cells or HemSC derived endothelial cells expressing EGFL6." (PMID 29340046, 2017).
Miscarriage (1 paper, 2015). A pregnancy that ends at a stage in which the fetus is incapable of surviving on its own, defined as the spontaneous loss of a fetus before the 22th week of pregnancy. "The remaining genes assayed had either very low or no expression in cultured chorionic villi from controls (PARK, LIPC, CTNNA3, EGFL6, GPM6B, RAB9A, POU6F2 and C7orf10) and were not assessed in miscarriages." (PMID 25674159, 2015).
osteonecrosis (1 paper, 2021). A none disease characterized by death of bone tissue due to a lack of blood supply. "Moreover, this enhanced understanding of the role of EGFL6 angiogenesis-osteogenesis coupling in the bone microenvironment may help to develop new diagnostic biomarkers and therapies for bone pathologies like osteoporosis and osteonecrosis." (PMID 34294121, 2021).
preeclampsia (1 paper, 2025). Preeclampsia is a hypertensive disorder of pregnancy that is characterized by new-onset hypertension with proteinuria presenting after 20 weeks of gestation, and depending on mild or severe forms may initially present with severe headache, visual disturbances, and hyperreflexia. "We observed a global decrease in EGFL6 in early onset preeclampsia, with concomitant increase in gene expression for placenta accreta across decidua, endothelial, and extravillous trophoblast cell types." (PMID 41141914, 2025). "In summary, our comparative analysis of early onset preeclampsia with placenta accreta identified trophoblast genes responsible for cell migration and invasion and highlighted the global contribution of EGFL6 and collagen at the maternal-fetal interface." (PMID 41141914, 2025).